IL1B (interleukin 1 beta)
Diseases named in the same sentence as IL1B in open-access papers (continued):
Sharing a sentence is not in itself a finding about the gene and the disease.
Allergy (continued). "Changed EP2 expression in children with allergies provides higher IL-1RI induction, increasing IL-1β capacity to increase COX-2 expression." (PMID 30620999, 2019). "A p < 0.0001 significant difference was recorded between the control and allergy groups in IL-1B serum concentration." (PMID 30620999, 2019). "We observed a significant 16.3-fold increase in IL-1β concentration in the allergy group compared to the control group, and this was similar to PBMCs behavior after stimulation with the tested substances." (PMID 30620999, 2019). "Our study produced similar results, where allergy group serum IL-1β concentration was significantly higher than controls." (PMID 30620999, 2019). "The current study demonstrated that IL-1β was strong risk factor to develop of moderate to severe PAR and other active allergic diseases, and therefore, it can be a biomarker of exacerbation or activation of allergic diseases, including AR." (PMID 31548841, 2019). "The primary role of the inflammasomes is to direct inflammation by controlling unregulated IL-1β release; therefore, IL-1β can be a significant marker of activation of allergic disease or severity." (PMID 31548841, 2019). "In human macrophages, DEHP treatment increases the production of inflammatory cytokines, such as TNF-α, IL-1β, IL-8, and IL-6, which induces the inflammatory response during allergic reactions." (PMID 31297340, 2019). "When an allergy model of house dust mite allergen was exposed to MWCNTs, the allergic response was prevented through suppression of IL-1β and pro-caspase-1 in alveolar macrophages." (PMID 30372450, 2018). "Inflammatory cytokines such as TNF-α, IL-1β, and IL-4 play crucial roles in prompting and sustaining chronic allergy." (PMID 26068872, 2015). "IL-1β aggravates auto-inflammatory and allergic diseases such as contact hypersensitivity, atopic dermatitis, and bronchial asthma." (PMID 26068872, 2015). "The levels of pro-inflammatory cytokines (IL-1β, IL-6, TNF), anti-inflammatory cytokine (IL-10), Th2-type cytokines associated with allergy (IL-4, IL-13, IL-33) and Th1-type cytokine (IFN-γ) were analysed from the treated skin sites of all groups." (PMID 25123235, 2014). "For instance, some recent data suggest that pro-inflammatory IL-1β may be of great importance in the development of allergic diseases and allergic inflammation." (PMID 40507979, 2025). "Furthermore, it is also worth mentioning that, in addition to the context of an allergy, MI has previously shown IL-1β-related anti-inflammatory potential and the capability to down-regulate IL1-β expression when using this same cytokine in ULD." (PMID 36675006, 2023). "More studies have found that IL-1β level was significantly increased in allergic diseases, and blocking the IL-1β signaling pathway may reduce the severity of inflammation to a certain extent." (PMID 37091903, 2023). "Overall, the strong involvement of IL-1β in allergic diseases means that treatments aimed at down-regulating this cytokine and its signaling pathways are attractive therapeutic options during acute and chronic manifestations to reduce the symptoms of IgE-mediated inflammation." (PMID 36675006, 2023). "In addition, some epithelial cells previously thought not to produce cytokines, such as epithelial cells in the respiratory tract, epidermis, and digestive tract, have also been reported to release IL-1β in allergic diseases." (PMID 37091903, 2023). "Pro-inflammatory cytokine IL-1β is a key mediator in infectious, autoimmune, and allergic diseases." (PMID 37629528, 2023). "In addition, based on the findings by our team, we provided new insights into the use of IL-1β in AR diagnosis and treatment, in an attempt to further promote the clinical application of IL-1β in AR and other allergic diseases." (PMID 37091903, 2023).
Allergy (continued). "Of course, IL-1β can also directly act on mast cells to enhance the release of cytokines and histamine secreted by mast cells and promote their response to other relevant cytokines, thereby assisting in the induction and maintenance of allergic reactions." (PMID 37091903, 2023). "Among patients with delayed-type hypersensitivity, the concentrations of most cytokines were slightly lower, while the level of interleukin 1 beta was significantly (p < 0.05) higher compared to the control group and significantly (p < 0.05) lower in comparison with IgE-mediated allergy patients." (PMID 35805534, 2022). "This study compared Th1 (IL-2) and Th2 (IL-4) parameters, anti-inflammatory, pro-inflammatory, or regulatory profile regarding both IgE levels and reported allergies, by means of clinical manifestations and IgE, IL-1β, IL-2, IL-4, IL-17, and TGF-β serum concentration." (PMID 34518597, 2021). "This process might be aggravated in the context of allergic diseases where IgE-triggered degranulation might enhance extracellular conversion of pro- into mat-IL-1β." (PMID 25184735, 2014). "The analysis implicated a number of genes with roles in allergy and inflammation, including pro-inflammatory cytokines (IL1A, IL1B, IL6, IL8 and TNF) and factors involved in immune cell activation and recruitment (SELE, SELL, SELP, ICAM1, CSF2, CSF3, CCL2 and CXCL2)." (PMID 21067579, 2010). "In 20 individuals who completed the survey (average age 46 years, 75% females), allergy to house dust was significantly associated with increased IPDI (adjusted for age) and significantly increased odds of potentially unhealthy values of total IgA, IL-1β, and CRP." (PMID 39910646, 2025). "However, Bianca found that mice treated with low doses of venom could induce mast cell degranulation and the secretion of MCP-1, IL-6, and IL-1β compared with PBS treated group, suggesting that some patients may be at risk of drug allergy after using “Wugong”." (PMID 35959238, 2022). "The study findings indicate that children with allergic diseases exhibit higher concentrations of both TSLP and IL-1β compared to healthy controls, supporting the role of the cytokines in promoting and sustaining allergic inflammation." (PMID 39860604, 2025). "In a study on the blood serum of intact rats anesthetized with TZX mixture, the levels of interleukin 1 beta (IL-1β) and tumor necrosis factor alpha (TNF-α) were barely determined, and TZX anesthesia is already used in animal models of allergic reactions." (PMID 35203719, 2022). "However, no eye rubbing or scratching was observed during the period of allergy induction in our study, while elevated TNF-α, IL-1β, and IL-6 mRNA levels were still confirmed." (PMID 35692541, 2022). "Similar to the pro-apoptotic of BCL2L12 in IL-1β-stimulated chondrocytes, BCL2L12 participated in the induction of aberrant Th2-biased inflammation in the intestinal mucosa and chronic rhinosinusitis with allergy." (PMID 34116684, 2021). "Collectively, these results suggest that eosinophils count, IL-1β and CCL-24 were overexpressed in children with moderate to severe PAR and with other active allergic diseases and therefore, can be used as a biomarker of exacerbation or activation of allergic diseases including AR." (PMID 31548841, 2019). "A binary classification of TGF-β activity as either high (in the presence of IL-1β and IL-6) or low (in the presence or absence of IL-1β and IL-6) is proposed to differentiate between allergy patients prone to cancer and metabolic dysregulations and those less prone." (PMID 38629073, 2024). "However, the specific effects and mechanisms of IL-1β and its receptors on AR and other allergic diseases have not been fully elucidated and warrant further exploration." (PMID 37091903, 2023). "However, such IL-1β-targeted drugs are rarely applied in the clinical treatment of AR, and most relevant studies were conducted in mouse models of allergic diseases, and no clinical study has been published so far." (PMID 37091903, 2023).
Allergy (continued). "However, consistent with this latter result, although not significantly altered by HDM‐induced allergy, IL‐1β mRNA levels are reduced by 12b treatment in this model." (PMID 27059010, 2016).
fibrosis (72 papers, 2010 to 2026). the formation of excess fibrous connective tissue in an organ or tissue in a reparative or reactive process. "Neutrophils participate in the pathogenic inflammatory and cardiac fibrosis process in viral myocarditis, with Il1β being the major driver of this process." (PMID 37534129, 2023). "Given that IL-1β–deficient mice are protected from silica-induced lung inflammation, and that administration of exogenous recombinant IL-1β causes pulmonary inflammation and fibrosis, IL-1β appears to be a critical mediator of silicosis." (PMID 24681489, 2014). "First, atelectasis-related mucus plugs can activate NLRP3 inflammasomes, promote the release of proinflammatory cytokines such as IL-1β, and aggravate peribronchiolar fibrosis." (PMID 40654577, 2025). "These suggested that SPP1+ Mac gradually replaces IL1B+ Mac as the primary intercellular signals during LFH fibrosis, exerting a more pronounced regulating influence." (PMID 40001138, 2025). "Immunohistochemistry showed that E-T/LNPs inhibited hepatic fibrosis by downregulating the levels of IL-1β and TGF-β." (PMID 39519763, 2024). "TNF-α, IL-1β, IL-6, and NF-κB are key players in orchestrating inflammatory responses that can lead to liver damage, fibrosis, and cirrhosis." (PMID 38999918, 2024). "We postulate that sterile inflammation, including the release of TNFα, IL-1β, IL-18 and IL-6, leads to changes in the endothelial-epithelial barrier and induces chronic fibrosis." (PMID 36993804, 2023). "Fibrosis is primarily driven by inflammatory cytokines including the IL-1β and TGF-b150, which can influence apoptosis." (PMID 37031239, 2023). "Over the past two decades, many studied have indicated that IL-1β, IL-6, and TNF-α are closely implicated in cardiac fibrosis, pathological cardiac remodeling, and cardiac hypertrophy." (PMID 34194329, 2021). "Previous studies in fibrosis mouse models and in cultured alveolar epithelial cells have demonstrated that inflammasome activity and ultimately the secretion of active IL-1β stimulates the production of TGF-β to mediate the development of lung fibrosis." (PMID 31873099, 2019). "During acute exacerbation of IPF, alveolar macrophages (AMs) and type II pneumocytes produce high levels of IL-1β in a mouse model of bleomycin-induced fibrosis." (PMID 29675024, 2018). "The content of TGF-β1 (up to 5033%) and IL-1β (up to 541%) in serum of mice with fibrosis on 3rd day of experiment was higher than that of serum from healthy mice, however the concentration of TNF-α was reduced (to 38%) compared with healthy mice." (PMID 25927611, 2015). "Our findings demonstrate the existence of an early IL-1β-IL-23-IL-17A axis leading to pulmonary inflammation and fibrosis and identify innate IL-23 and IL-17A as interesting drug targets for IL-1β driven lung pathology." (PMID 21858022, 2011). "We demonstrated recently the predominant role of the NLRP3 inflammasome activation and IL-1β expression in the establishment of pulmonary inflammation and fibrosis in mice." (PMID 21858022, 2011). "In this study, we report the involvement of IL-23p19 and innate IL-17A in the occurrence of pulmonary inflammation and fibrosis and demonstrate the critical role of IL-1β in these processes." (PMID 21858022, 2011). "Regarding IL-1β, other studies using MSCs as treatment for pulmonary inflammation and fibrosis showed a decrease in its expression, but this difference in our results could be attributed to the fact that we used CM and not the MSCs themselves." (PMID 35562961, 2022). "Many studies over the last two decades have shown that IL-1β, IL-6, and TNF-α are intimately linked to cardiac fibrosis, pathological cardiac remodeling, and cardiac hypertrophy, and the inflammatory cytokines induced following the activation of the nuclear factor-κB (NF-κB) pathway." (PMID 36164390, 2022). "In mice models the NLRP3/IL1-b axis is required for the development of bleomycin induced fibrosis." (PMID 34220810, 2021).
fibrosis (continued). "This pattern holds even after stratification of the patients into mild fibrosis and advanced fibrosis, demonstrating that the NLRP3-rs10754558 or another polymorphism in linkage disequilibrium with it possibly has an influence on the processing of pro-IL-1β." (PMID 34161370, 2021). "Our findings also demonstrate that Calhex231 may hinder ventricular fibrosis by inhibiting myocardial inflammation induced by macrophages and IL‐1β." (PMID 33043596, 2020). "On the other hand, the IL-1β rs1143634, which was shown recently to be associated with advanced fibrosis in nonalcoholic steatohepatitis in Caucasians, did not reveal any association with the fibrosis degree in HCV patients in our study." (PMID 30728751, 2019). "This increase also involved the ERK1/2 MAP kinase and NFκB pathways, which is consistent with previously reported data showing the active role of IL-1β in the pathogenesis of multiple pulmonary diseases, such as pulmonary infection, fibrosis, cancer, and emphysema." (PMID 23300722, 2012). "We speculated that IL-1β secreted upon lung injury may induce innate IL-23 and IL-17 expression in lung resulting in pulmonary inflammation and evolution to fibrosis." (PMID 21858022, 2011). "Additional studies have shown that uric acid released from injured cells constitutes a major endogenous danger signal that activates the NALP3 inflammasome (also called cryopyrin or NLRP3), leading to IL-1b production as part of the host response to lung inflammation and fibrosis." (PMID 20844590, 2010). "However, in line with a previous study examining gene expression of IL‐1β in SSc skin manifestation, together with the well‐described role of IL‐1β in fibrosis, we did observe a positive correlation between serum IL‐1β concentration and the mRSS index, particularly in patients with limited subtype." (PMID 30997045, 2019). "Our work highlighted the fact that local intrapleural treatment with an IL-1β inhibitor such as IL-1ra (to counteract BLM-induced pleural inflammation) limited fibrosis progression and could thus be a therapeutic option notably in the management of acute exacerbation of IPF." (PMID 27894300, 2016). "Second, in various animal fibrosis models, ketanserin was shown to decrease the levels of several cytokines such as TNF-α, IL-10, IL-1β, IL-8, and IL-633,35,36." (PMID 38228622, 2024). "In our study, IL-1β and NLRP3 expression levels were negatively correlated with MAFLD fibrosis grade, whereas NFS was positively correlated with MAFLD fibrosis grade." (PMID 39179677, 2024). "To further investigate the impact of AS/LIG/AS_LIG@PPGC NPs on pulmonary inflammation and fibrosis in IPF, we collected mouse BALF on Days 8 and 22 and measured the levels of IL-1β, IL-6, TNF-α, and TGF-β1 using ELISA." (PMID 38166847, 2024). "For example, Il1b is a potent inflammatory cytokine produced mainly by macrophages that participate in toxic-, ethanol- and NASH-induced fibrosis, and it has been found to prolong the survival of HSCs." (PMID 36814339, 2023). "The classic pro-inflammatory cytokines IL-6, IL-1β, and TNF-α have the effect of promoting fibrosis, which has been observed in fibrosis models of lung, heart, kidney." (PMID 37305520, 2023). "As the differentiation of Th17 cells from naïve T cells requires TGF-β, IL-6, IL-1β, and IL-23, the mRNA expression of these cytokines was investigated in lung tissues of BLM-induced fibrosis." (PMID 36674533, 2023). "B1R blockade with BI 113823 inhibited the accumulation of macrophages and neutrophils in both CCl4 and BDL fibrosis livers, and reduced the expression of inflammatory mediators, B1Rs, COX-2, IL-1β, IL-6, MCP-1, MCP-3 and TIMP-1 in liver tissue." (PMID 36514072, 2022). "After 8 weeks of the corresponding intervention, renal function, liver function, and protein expression of renal-fibrosis-related factors, HIF-1α, IL-1β, and c-Myc, were detected." (PMID 34211565, 2021).
fibrosis (continued). "Our results demonstrated that hepatic expression of TNF-α, IL-1β, and MCP-1 mRNA was strongly upregulated in BDL fibrosis models." (PMID 28744285, 2017). "PegHYAL was reduced the concentration of TNF-α (to 1.3%), IL-1β (to 72%), TGF-β1 (to 12.5%) in serum and TGF-β (to 11%) in BLM-injured lung compared to untreated mice with fibrosis." (PMID 25927611, 2015). "Measuring IL-1β, IL-18, CTGF, and TNF-α in BAL fluid along with pulmonary function tests may enable early diagnosis of patients who will develop fibrosis." (PMID 41302962, 2025). "Notably, L. minor lung protection markedly decreased in the IL-1β levels (by 38.82 ± 5.41, p < 0.0003, t-test) and TNF-α levels (by 232.87 ± 35.09, p < 0.0062, t-test), compared to BLM-induced fibrosis group, on the course 33 days, respectively." (PMID 35326173, 2022). "Previous studies revealed that TMAO may exacerbate cardiac fibrosis and inflammation induced by high glucose levels via upregulating the proinflammatory cytokines TNF-α and IL-1β." (PMID 31354519, 2019). "The expression levels of IL-1β, IL-6, IL-17, TNF-α, TGF-β, and α-SMA (as a myofibroblast marker) were all decreased by anakinra treatment, which suggested anti-inflammatory and antifibrotic effects of the IL-1Ra in this BLM-induced fibrosis model." (PMID 30042768, 2018). "Four studies determined a significant association between IL‐1b and HCC in HCV‐infected patients, whereas two studies investigated the association with cirrhosis and fibrosis and found no such association." (PMID 29397014, 2018). "Some proteins of these genes have already been associated with pathophysiological processes in the kidney: in tubulointerstitial fibrosis (c-MYC, PTEN, STAT3, HIF-1α, PT53); podocyte injury (EGFR, PT53, CTNNB1, CREB1); epithelial-mesenchymal transition (PTEN); and glomerulosclerosis (DICER1, IL1β)." (PMID 37035314, 2023). "BLM administration increase lung concentrations of IL-1β (69.16 ± 2.69 vs. 27.36 ± 1.37, p < 0.005, t-test), IL-6 (104.7 ± 13.45 vs. 17.466, p < 0.02, t-test), and TNF-α (500.09 ± 42.19 vs. 58.84 ± 4.51, p < 0.05, t-test) observed in BLM-induced fibrosis group, compared to controls." (PMID 35326173, 2022). "Researches show that chronic liver inflammation may lead to fibrosis and cirrhosis through IL-1signaling.And IFI16 can stimulate cleavage of pro-IL1b and pro-IL18 to the bioactive cytokines.So IFI16 may play a role in the pathogenesis of liver cirrhosis, next step we can further investigate it." (PMID 29743020, 2018).